CD82 (CD82 molecule)
Diseases named in the same sentence as CD82 in open-access papers (continued):
Sharing a sentence is not in itself a finding about the gene and the disease.
tumor (continued). "Notch4 (a marker of Notch signaling pathway receptors), DLL4 (a marker of Notch signaling pathway ligands) and KAI1/CD82 (a suppressor gene of tumor metastasis) are all effective predictive factors for tumor metastasis." (PMID 30593175, 2018). "CD82 overexpression correlates with reduced cell growth, migration, invasion and xenograft tumor growth in OSCC, and CD82 downregulation is associated with poorer survival in OSCC." (PMID 30005669, 2018). "Some tumor-associated stromal cells can produce tumor suppressor factors, such as nucleoside NME1, Kangai 1 (KAI1/CD82) and IL-25, in the tumor microenvironment, and these activities can restrict the development or metastasis of surrounding tumor cells." (PMID 28674499, 2017). "Overall, these results demonstrate a CD82 function in the suppression of the tumor cell-intrinsic migrating and invasive potential, which corresponds to its EMT-suppressing role." (PMID 27926483, 2017). "In conclusion, CD82 was down-regulated in RCC and positive CD82 expression was significantly associated with tumour stage, histological grade and tumor size." (PMID 28881668, 2017). "We found that CD82 was down-regulated in RCC tissues and cells and its expression was significantly associated with histological grade(p=0.041), tumour stage (p=0.036) and tumor size(p=0.020) by analyzing tissue microarrays." (PMID 28881668, 2017). "The tetraspanin KAI1/CD82 was identified as a tumor metastasis suppressor that downregulated in various malignant cell types." (PMID 28881668, 2017). "Knockdown of LAMC2 (or rescue of miR-622) expression or knockdown of miR-197 (or rescue of CD82) expression in MGC-803 cells inhibited tumor cell invasion." (PMID 28252644, 2017). "HBx can inhibit the expression of CD82, a tumor suppressor gene that prevents metastasis, through hypermethylation of CD82 promoter." (PMID 27314335, 2016). "We here investigated the effects of the metastasis suppressor CD82/KAI1 on the process of heterocellular adhesion of tumour cells to the endothelium of blood vessels, in order to further elucidate the function of tetraspanins." (PMID 25923697, 2015). "In summary, low expression of KAI1/CD82 combined high expression of CD44, MMP7 and β-catenin was found to be associated with tumor metastasis and poor prognosis in CRC." (PMID 26408312, 2015). "CD82 can inhibit tyrosine phosphorylation of β-catenin and stabilize E-cadherin-β-catenin complexes and, thus, prevent tumor cell dissemination from primary tumors." (PMID 25889325, 2015). "In this study, we analyzed the tumor metastasis related factors KAI1/CD82, CD44, MMP7 and β-catenin, to provide a new direction for investigating the metastasis and prognosis of CRC." (PMID 26408312, 2015). "CD82 gene is a suppressor of metastasis of tumor in many tumors and a member of the tetraspanins superfamily of glycoproteins." (PMID 25889325, 2015). "The KAI1/CD82 gene exhibits an inhibitory function with regard to tumor metastasis, and this inhibition has been confirmed in a number of studies investigating malignant cancer." (PMID 25789023, 2015). "It is suggested that CSCs, angiogenesis, and CD82 be possible as a therapeutic marker for anti-tumor therapy." (PMID 25889325, 2015). "The existence of a possible relation between COX-2 and KAI-1/CD82 was confirmed by the presence of an inverse correlation in the expression of the two genes in 55 tumor samples of PTC." (PMID 28548071, 2014). "The tetraspanin superfamily proteins (TM4SF) mainly CD9, CD63, CD82, CD151 and CD81 have been implicated in cell migration, proliferation and tumor cell metastasis." (PMID 23128478, 2013). "CD82 is a member of transmembrane 4 superfamily, which showed important role in inhibiting tumor cell invasion and migration." (PMID 22679510, 2012).
tumor (continued). "In contrast, 63 patients (43.2%) had KAI1/CD82-positive tumours and the overall survival rate of patients with KAI1/CD82-positive tumours was also higher than that of patients with KAI1/CD82-negative tumours (84.8 vs 54.9%, P=0.002)." (PMID 12838318, 2003). "With respect to pathological stage, the percentage of patients whose tumours had KAI1/CD82-negative gene expression increased from 40.0% of those with stage I to 73.3% of those with stage III." (PMID 12838318, 2003). "If SRCC constitute the major dormant cancer population (or one of them), riboflavin fluorescence (or SLC52A1-3), NOTCH1, and CD82, may serve as reliable markers for the clinical assessment of tumor cell dormancy and prediction of relapse." (PMID 41453945, 2025). "Additionally, we found an association between elevated expression of liprin-α1 and weak expression of CD82 in tumor cells (p = 0.029)." (PMID 37335526, 2023). "In addition, we also found that RGS1 and CD82 were co-over-expressed by all tumor lesions for all four MPLCs patients." (PMID 37488117, 2023). "Furthermore, we found that elevated liprin-α1 expression in tumor cells correlated with weak tumor expression of CD82, which is in line with a previous finding." (PMID 37335526, 2023). "Moreover, many researchers currently recognize that CSCs are characterized by high expression of CD29, CD44, CD82, or CD133, which are associated with tumor progression and stemness in various cancers." (PMID 37182132, 2023). "In addition, DARC has been found to interact with the tumor suppressor protein KAI1 (CD82), which plays a crucial role in inhibiting tumor cell proliferation and promoting senescence." (PMID 37242305, 2023). "We found significant correlation between liprin-α1 and CD82 expression in tumor cells (p = 0.029)." (PMID 37335526, 2023). "Moreover, in most cases, the mechanism of action of several of our compounds involves enhancement of KAI1/CD82 RNA level depending on the specific compound and the human tumor type." (PMID 37990044, 2023). "Notably, only two genes including regulator of G-protein signaling 1 (RGS1) and CD82 were classified into the Same type for all four MPLCs patients with higher expression in tumor tissues than normal tissues." (PMID 37488117, 2023). "Accumulated evidence has shown that CD82 is a potent tumor suppressor." (PMID 36386228, 2022). "In addition to KAI1/CD82 role of mediating tumor aggression, the protein was observed to play a critical role in virus receptor coordination (binding) and entry into cells." (PMID 34121877, 2021). "While the role of CD82 in the modulation of cancer-/metastasis-related pathways is not well understood, several studies have demonstrated that CD82 influences tumor cell migration and invasion by affecting integrin function or through association with EWI-2 and CD81." (PMID 34445169, 2021). "KAI1/CD82 level was negatively correlated with tumor size, metastasis, and TNM stage in NSCLC." (PMID 34306081, 2021). "CD82 also has the ability to interact with different molecules in the tumor microenvironment." (PMID 34830819, 2021). "The protein expression levels of CD82 in the tumours were also investigated by immunoblotting." (PMID 34503110, 2021). "Expression of CD82 is downregulated during tumour progression of human cancers." (PMID 34503110, 2021). "Since CD82 is down-regulated in advanced cancers, its role as a suppressor of tumor metastasis has been studied in detail, whereas its role in pancreatic development has remained unknown." (PMID 33953224, 2021). "CD82 expression was significantly decreased in tumour versus normal lung tissue (p < 0.001), while there was also a significant difference between tumour types as only 6% of the LUAD samples were found positive for CD82 expression compared to 22% of LUSC patient samples (p < 0.05)." (PMID 34503110, 2021).
tumor (continued). "NF-κB RelA/p65 promotes lung epithelial cell tumour growth in vivo by downregulating the metastasis suppressor CD82 and enhancing the epithelial-to-mesenchymal cell transition via integrin-mediated signalling involving the mitogenic ERK, Akt1 and Rac1 proteins." (PMID 34503110, 2021). "CD82 acts as a tumor suppressor in a series of steps in malignant progression." (PMID 33204367, 2020). "On the contrary, ACKR1 was reducing tumor growth in a model of prostate cancer through the binding of angiogenic ELR+ CXC-chemokines that decreased angiogenesis and in a melanoma lung metastasis model, interacting with the tetraspanin CD82/KAI that induced tumor cells senescence." (PMID 30894861, 2019). "VM and the expression of Notch4, DLL4, and KAI1/CD82 represent promising markers for tumor metastasis and prognosis, and maybe potential therapeutic targets for NSCLC." (PMID 30593175, 2018). "The following results may revealed how CD82 act as a tumor suppressor in RCC cell lines and provide a potential biomarker for treatment of RCC." (PMID 28881668, 2017). "In addition, we first detected CD82 as a potential tumor suppressor in RCC by inhibiting TGF-β/Smad signaling pathway and play a crucial role in RCC migration and invasion." (PMID 28881668, 2017). "Consequently, we suggested the aberrant expression of CD82 can act as a tumor suppressor and therapeutic target for treating RCC." (PMID 28881668, 2017). "Furthermore, in 36 of 55 cases, tumor areas contained lower levels of KAI-1/CD82 RNA as compared with the corresponding normal tissue." (PMID 28548071, 2014). "CD82/KAI1 acts as a tumor suppressor modulating the activities of EGFR." (PMID 25278937, 2014). "Indeed, it has been previously reported that CD82 suppresses tumor invasion by MMP9 inactivation via TIMP1 up-regulation in carcinoma cell line." (PMID 22679510, 2012). "It appears therefore that DARC may negatively affect tumor development and metastatic spread either directly by binding to CD82 or by removing angiogenic chemokines from perivascular spaces." (PMID 22912641, 2012). "Additionally, advanced and metastasized tumor tissues revealed significantly down-regulated CD82 protein expression (p = 0.033 and p = 0, respectively), which correlated with the tumor pTNM stage (p = 0.001)." (PMID 21521534, 2011). "CD82, as a suppressor of tumor cell metastasis, have the clearest mechanisms of the three members." (PMID 21521534, 2011). "Of the 20 known members, five – MRP1/CD9, ME491/CD63, KAI1/CD82, CD151, CD81 – may be implicated in cell migration, proliferation and tumour cell metastasis." (PMID 14735195, 2004). "Furthermore, strong liprin-α1 expression in tumor tissue correlated with weak CD82 staining." (PMID 37335526, 2023). "Furthermore, it is possible ACKR1 could contribute cell cycle regulation through other interactions including the tumor suppressor CD82/KAI1, a multifunctional surface tetraspanin." (PMID 37006247, 2023). "Therefore, the effects of CD82 in suppressing E-cadherin shedding from cell membrane may influence multiple steps of tumor progression through various pathways." (PMID 33204367, 2020). "Our current study may not only be helpful to reveal the mechanisms underlying the invasion- and metastasis-suppressing role of CD82/KAI1, but also contribute to the comprehensive understanding of the EMT program under the control of the pericellular matrix in tumor microenvironments." (PMID 27926483, 2017). "Indeed, inhibition of CDCP1 expression via KAI1/CD82 in an in vivo tumor xenograft model, leads to significantly decreased levels of hypoxia-inducible factor-1α (HIF-1α) and one of its key down-stream targets, the angiogenesis promoting protein vascular endothelial growth factor-1 (VEGF-1)." (PMID 26431493, 2015). "Furthermore, elevating the degradation of CD82 promotes tumor metastasis in mice." (PMID 19671175, 2009).
tumor (continued). "In addition, reduced expressions of metastatic suppressor genes, such as E-cadherin, MRP-1/CD9, and KAI1/CD82, could induce tumour cells with high metastatic potential." (PMID 15785747, 2005). "The interaction between CD82 and DARC triggers an intracellular signaling cascade and induces tumor cell senescence." (PMID 40299574, 2025). "MiR‐31 represses tumour suppressors DACH1 and CEBPA, which otherwise direct the CD9, CD82 and AXIN1 expression." (PMID 38797942, 2024). "CD82/KAI1 belongs to the transmembrane 4 superfamily and is considered a critically important tumor metastasis suppressor." (PMID 38534734, 2024). "Conversely, Tspan7, CD82, CD63, Tspan7, and Tspan9 are downregulated, suppressing digestive system tumor cell metastasis." (PMID 38389703, 2024). "TCGA database analysis revealed that E2F7, CD82, and TNNC1 showed significantly higher expression in tumor tissues than in normal tissues." (PMID 36612299, 2023). "Several other tetraspanins including CD82 and CD151 have been identified as tumor suppressors or oncogenic in multiple cancer types owing to their ability to regulate tumor cell metastasis." (PMID 35524311, 2022). "CD82 can weaken the EGF/EGFR induction signal and inhibit tumor metastasis, but the mechanism is still unclear." (PMID 35538033, 2022). "Next, we investigated the expression of CD82 and ROS1 mRNA by real-time qPCR in vector control and RelA/p65KD A549 and H1437 cancer cells grown as tumour xenografts in mice." (PMID 34503110, 2021). "Transcriptome analysis of vector control and Rel/p65KD A549 and H1437 cell tumours identified the proto-oncogene ROS1 and the LGR6 receptor gene amongst the downregulated genes, and the metastasis suppressor CD82 as one of the upregulated genes." (PMID 34503110, 2021). "Based on the RNA-seq data, we observed that genes that suppress tumor angiogenesis, including SERPINE1, THBS1, SERPINB5, CD82 and ANGPTL4, were upregulated." (PMID 32106543, 2020). "CD82, a protein product of the KAI-1 or CD82 gene, was first identified as a metastasis tumor suppressor in rat prostate cells in 1995." (PMID 33298014, 2020). "To date, many tumor metastasis- and invasion-related studies have focused on CD9, CD81, CD82/KAI1, CD151, and TM4SF1." (PMID 30876464, 2019). "For example, the tetraspanin CD82 is downregulated during metastases, while the tetraspanin CD151 and tetraspanin 8 are induced and able to support tumor progression." (PMID 31437164, 2019). "In our study, multivariate analysis showed that VM, expression of Notch4, DLL4, and KAI1/CD82, as well as TNM stages, tumor size, DM, and LNM, were independent prognostic factors for NSCLC patients." (PMID 30593175, 2018). "Our findings thus demonstrated that VM, Notch4, DLL4, and KAI1/CD82 were reliable biomarkers for NSCLC, and especially in predicting tumor metastasis and prognosis." (PMID 30593175, 2018). "The role of tumor suppression genes/proteins is also involved, CD82 expression on CPCs, the product of the tumor suppressor gene KAI1, impedes adhesion of the tumor cell to endothelial cells by inhibiting crosstalk with the Duffy antigen receptor." (PMID 30180883, 2018). "In multivariate analysis, high VM, Notch4, DLL4 levels, tumor size, LNM, DM, TNM stage, and low KAI1/CD82 levels were potential to be independent prognostic factors for overall survival time (OST) in NSCLC patients." (PMID 30593175, 2018). "Second, DARC interacts with the tumour suppressor protein KAI1 (CD82), leading to the inhibition of proliferation and increased senescence of tumour cells." (PMID 30381365, 2018). "Higher levels of miR-197 via downregulation of CD82 in coordination with lower levels of miR-622 via upregulation LAMC2 in GC activate EGFR-ERK1/2 signaling, thus having a role in promoting tumor cell invasion and metastasis." (PMID 28252644, 2017).
tumor (continued). "The expression of KAI1/CD82, CD44, MMP7 and β-catenin is related to tumor metastasis and prognosis in CRC." (PMID 26408312, 2015). "Knockdown of Cx32 significantly suppressed the expression of CD82 and enhanced the expression of PCNA in transplanted tumor tissue." (PMID 25426556, 2015). "Overall, these results indicate that there is a complex relationship between the KAI1/CD82, CD44, MMP7 and β-catenin in tumor progression." (PMID 26408312, 2015). "CD82, a tetraspanin which was identified as a prostate cancer metastasis suppressor gene, apparently directly interacts with DARC which thus can inhibit tumor cell proliferation and induce senescence." (PMID 22912641, 2012). "To determine how tetraspanin KAI1/CD82, a tumor metastasis suppressor, inhibits cell migration, we assessed which cellular events critical for motility are altered by KAI1/CD82 and how KAI1/CD82 regulates these events." (PMID 23251627, 2012). "Consistent with this, the tetraspanins, CD82 and CD9, possessing tumour supressor properties, down-regulate Wnt signaling through the exosomal discharge of β-catenin." (PMID 23173708, 2012). "We herein demonstrated that, as a tumor metastasis suppressor, KAI1/CD82 inhibits cell movement by attenuating the formation and development of both cellular protrusion and retraction at the cellular level." (PMID 23251627, 2012). "KAI1 (CD82), a TSG on chromosome 11p11.2, regulates adhesion, migration, growth, and differentiation of tumor cell lines." (PMID 22481931, 2012). "The tetraspanins CD82 and CD9 mostly suppress tumour progression; their expression is often reduced in late-stage human tumours and their down-regulation during CRC progression is associated with poor prognosis." (PMID 21339979, 2010). "Tetraspanins are small transmembrane proteins, such as CD9, CD37, CD53, CD63, CD81, CD82, CD151 and tetraspanin 8, that are involved in a multitude of biological processes, including cell-cell adhesion, metastasis suppression and tumour progression." (PMID 21339979, 2010). "Furthermore, a survival analysis was conducted on the individual genes comprising the UBE2C+ tumour cell score, and it revealed statistically significant results for ITPRIP, GJA1, RUNX1T1, CD82, PAPSS2 and ANXA5." (PMID 38894657, 2024). "In contrast, differentially expressed genes between CECs isolated using the cmHsp70.1 mAb- versus EpCAM mAb-based approach, such as ROCK2, STAT3 and CD82, are related to EMT, stemness and endometrial cell proliferation, which are regulated via up-regulated CD44/STAT3 signaling in tumor cells." (PMID 39519195, 2024). "Further, among HPV-positive patients, we found an association with strong liprin-α1 expression and concurrent negative or weak CD82 expression in tumor cells (p = 0.006)." (PMID 37335526, 2023). "To assess the potential of these biomarkers in the management of HPV-positive and HPV-negative OPSCC, we compared the expression of liprin-α1 and CD82 in tumor cells to clinical characteristics and survival of the patients." (PMID 37335526, 2023). "The majority of the patients (77.4%) among the whole cohort presented negative or weak CD82 expression in tumor cells." (PMID 37335526, 2023). "Among HPV-negative patients, there was a moderate correlation between current smoking habit and negative or weak CD82 expression in tumor cells (p = 0.048)." (PMID 37335526, 2023). "Lastly, we found that the majority of large tumors (>6 mm3) were negative for CD82, while in contrast, CD82 positive tumors represented about 61% of smallest tumor samples (<5 mm3, p = 0.027)." (PMID 34065085, 2021).